FOXA1 (forkhead box A1)
Diseases named in the same sentence as FOXA1 in open-access papers (continued):
Sharing a sentence is not in itself a finding about the gene and the disease.
endometrial cancer (16 papers, 2013 to 2023). Primary or metastatic malignant neoplasm involving the endometrium (mucous membrane that lines the endometrial cavity). "Also, the recent publication by The Cancer Genome Atlas (TCGA) Research Network showed low ER/FOXA1 signaling to be associated with poor survival in endometrial cancer." (PMID 24849812, 2014). "Our finding that FOXA1 protein expression increase from primary tumors to metastases, could appear as contradictory to our finding that high FOXA1 associates with good outcome in patients with endometrial cancer." (PMID 24849812, 2014). "A previous study of endometrial cancer found that FOXA1 knockdown reduces the rate of tumor growth in an in vivo xenograft model." (PMID 35968505, 2022). "On the other hand, AR was required for FOXA1-enhanced Notch pathway activation in endometrial cancer cells, increasing Notch1 and HES1 expression." (PMID 33167316, 2020). "MiR-93 transfection in the endometrial cancer cells downregulated FOXA1 expression while miR-93 inhibitor transfection upregulated FOXA1 expression significantly." (PMID 27829043, 2016). "Immunohistochemistry has shown that FOXA1 expression is negatively related to lymph node metastasis, and downregulating FOXA1 promotes endometrial cancer cell proliferation and migration." (PMID 27829043, 2016). "Above all, we suggest that miR-93 promote EMT, migration, and invasion in endometrial carcinoma cells through downregulating FOXA1." (PMID 27829043, 2016). "Endometrial carcinoma cells were transfected with FOXA1 siRNAs (siFOXA1, siFOAX1-1, and siFOXA1-2) to downregulate FOXA1 expression." (PMID 27829043, 2016). "The transcription factor Forkhead box A1 (FOXA1) is suggested to be important in hormone dependent cancers, although with little data for endometrial cancer." (PMID 24849812, 2014). "We investigated expression levels of FOXA1 in primary and metastatic endometrial cancer in relation to clinical phenotype, and transcriptional alterations related to FOXA1 status." (PMID 24849812, 2014). "Little is known regarding bindingpartners for FOXA1 in endometrial cancer, and more work is needed to elucidate this." (PMID 24849812, 2014). "We investigated a large and unique collection of endometrial cancer samples to elucidate a potential similar role for FOXA1 in these diseases." (PMID 24849812, 2014). "This appears to be in line with an endometrial cancer cell line study demonstrating that introduction of FOXA1 suppresses both proliferation and migration in contrast to ERα which leads to proliferation." (PMID 24849812, 2014). "Low FOXA1 is associated with poor survival and suggests a potential for HDAC inhibitors in endometrial carcinoma." (PMID 24849812, 2014). "Protein expression of FOXA1 was explored by immunohistochemistry in 529 primary and 199 metastatic endometrial carcinoma lesions." (PMID 24849812, 2014). "In endometrial cancer tumors, FOXA1 is expressed in 37 % of the cases, and its expression is significantly and negatively associated with lymph node status." (PMID 23192763, 2013). "Forced expression of FOXA1 in endometrial cancer cells leads to cellular senescence." (PMID 32201519, 2020). "In addition, transfection with the most effective FOXA1 small interfering RNA promoted both endometrial cancer cell migration and invasion, and downregulated E-cadherin expression while upregulating N-cadherin expression." (PMID 27829043, 2016). "We transfected endometrial carcinoma cells with siFOXA1 to downregulate FOXA1 expression, and found upregulated N-cadherin expression, downregulated E-cadherin expression, and promoted migration and invasion ability, which demonstrates that FOXA1 acts as a suppressor in EMT." (PMID 27829043, 2016). "FOXA1 seems to have tissue specific roles that also may change during endometrial cancer progression." (PMID 24849812, 2014).
endometrial cancer (continued). "Interestingly, in ER-positive endometrial cancer cells, FOXA1 has been suggested to function as a tumor suppressor through modulation of proliferation and migration of endometrial cancer cells." (PMID 23192763, 2013). "In summary, all the published data suggest that the idea of using FOXA1 as a therapeutic target in breast and endometrial cancers could be an alternative for those patients with recurrence to current treatments." (PMID 23192763, 2013). "Therefore, we suggest that miR-93 may promote the process of epithelial–mesenchymal transition in endometrial carcinoma cells by targeting FOXA1." (PMID 27829043, 2016). "Thus, FOXA1 may add clinically relevant information as a biomarker in endometrial cancers and points to a role for HDAC inhibitors for treatment." (PMID 24849812, 2014). "The higher expression of FOXA1 in metastases compared to their primary tumor counterparts, and the association between protein expression of FOXA1 and CDKN2A mRNA only in metastatic lesions, may indicate a change in the role of FOXA1 during endometrial cancer progression." (PMID 24849812, 2014). "However, the exact function and mechanism of FOXA1 in human endometrial cancer (EC) remains unclear." (PMID 24512546, 2014). "This could indicate that FOXA1 in endometrial cancer may have a function that is not linked to ERα, and the effect of FOXA1 could be organ specific." (PMID 24849812, 2014). "In addition, it is likely that other unknown factors than FOXA1 is required for regulation of ERα function in endometrial cancer." (PMID 24849812, 2014). "The impact of changes in OGT and TET3 amounts on the expression of genes involved in epithelial-mesenchymal transition (FOXA1, FOXC1, TWIST, ZEB1) in endometrial cancer cells has been analyzed." (PMID 34948036, 2021). "PGR (Progesterone receptor), FOXA1 (Forkhead box protein A1), XBP1 (X-box binding protein 1), and TFF1 (Trefoil factor 1) were reported to involve in the estrogen signal in endometrial cancer." (PMID 33324448, 2020). "Our findings report for the first time that miR-93 promotes endometrial carcinoma cell EMT, migration, and invasion via targeting downregulation of FOXA1, which differs from its anti-oncogene role in ovarian cancer." (PMID 27829043, 2016).
gastric cancer (16 papers, 2012 to 2025). A primary or metastatic malignant neoplasm involving the stomach. "Moreover, it is more important to reveal that the positive expression of FOXA1 is associated with poor clinicopathological features and poor prognosis in patients with gastric cancer." (PMID 32411194, 2020). "Therefore, this present study used a case-control method to compare the genotypes and alleles of FOXA1 gene rs12894364 and rs7144658 in gastric cancer patients and healthy controls to analyze the relationship between FOXA1 gene polymorphism and gastric cancer susceptibility." (PMID 32411194, 2020). "In addition, clinical association analysis showed that positive FOXA1 expression was associated with poor clinicopathological features in patients with gastric cancer, including poor tumor differentiation, large tumor size, and advanced stage of lymph node metastasis." (PMID 32411194, 2020). "Existing studies have shown that the expression of FOXA1 affects the proliferation and invasion of gastric cancer cells." (PMID 35812327, 2022). "In esophageal squamous cell and in gastric carcinoma, where KRT7 overexpression is associated with a poor prognosis, KRT7 was transcriptionally upregulated by FOXA1." (PMID 34070214, 2021). "Gastric cancer is divided into intestinal type, diffuse type, and mixed type according to Lauren type, and FOXA1 expression state is different in different types of gastric cancer." (PMID 32411194, 2020). "A significant increase in mRNA and protein levels of FOXA1 was observed in gastric cancer tissues compared to adjacent tumor tissues." (PMID 32411194, 2020). "The potential carcinogenic role of FOXA1 in gastric cancer has led us to investigate its biological role." (PMID 32411194, 2020). "The levels of FOXA1 protein and mRNA in gastric cancer tissues were significantly higher than those in adjacent tumor tissues." (PMID 32411194, 2020). "In vivo studies showed that FOXA1 knockdown significantly inhibited tumor growth in gastric cancer in nude mouse xenograft models." (PMID 32411194, 2020). "In gastric cancer, FOXA1 acts as an oncogene by inhibiting apoptosis and activating cell proliferation rate." (PMID 32685483, 2020). "Both in vitro and in vivo studies have demonstrated that FOXA1 inhibition can inhibit the proliferation and induce apoptosis of gastric cancer cells." (PMID 32411194, 2020). "In gastric carcinoma, FOXA1 promotes tumor cell proliferation, migration and invasion ability." (PMID 34991620, 2022). "Therefore, FOXA1 can be a promising prognostic indicator and an attractive therapeutic target for gastric cancer." (PMID 32411194, 2020). "Notably, the 5-year overall and relapse-free survival of gastric cancer patients with FOXA1 positive expression was poor." (PMID 32411194, 2020). "Therefore, FOXA1 is expected to be a novel biomarker with significant value in predicting the clinical outcome of gastric cancer patients." (PMID 32411194, 2020). "Similarly, in gastric cancer cells, FOXA1 regulates the EMT in cancer cells, by inducing the E-cadherin expression and decreasing the vimentin protein level." (PMID 32685483, 2020). "Therefore, our data suggest that FOXA1 plays a carcinogenic role in gastric cancer by promoting cell proliferation and preventing apoptosis." (PMID 32411194, 2020). "UGT2B15 may upregulate FOXA1 and activate the hippocampal-yap signaling pathway to promote the development of gastric cancer." (PMID 32010623, 2019). "There is no research on the relationship between FOXA1 gene polymorphism and gastric cancer." (PMID 32411194, 2020). "The clinical significance of FOXA1 and its biological function in gastric cancer remains unknown." (PMID 32411194, 2020). "However, the biological function of FOXA1 in gastric cancer tissues is still unclear." (PMID 32411194, 2020). "Therefore, we hypothesized that FOXA1 might regulate the proliferation and apoptosis of gastric cancer cells by regulating the expression of YAP." (PMID 32411194, 2020).
gastric cancer (continued). "There was an opposite OS trend in HER2-negative patients, while all gastric cancer patients combined showed a significant positive correlation between high mean JAM-A, HER2 and FOXA1 expression and poor OS similar to that in the HER2-positive population alone." (PMID 35203384, 2022). "Therefore, the results may have certain limitations so that the association between FOXA1 gene and gastric cancer cannot be completely ruled out." (PMID 32411194, 2020). "FOXA1 directly binds to the MND1 promoter to suppress its transcription, and this suppression-mediated activation of the PI3K/AKT signaling axis concomitantly inhibited gastric cancer progression and enhanced oxaliplatin chemosensitivity." (PMID 40623983, 2025).
ovarian carcinoma (16 papers, 2016 to 2026). A malignant neoplasm originating from the surface ovarian epithelium. "Through experimental verification, we found the underlying function of FOXA1 to promote EMT in ovarian cancers." (PMID 36393971, 2022). "To further examine the association between the development of EMT and FOXA1-CTGF-TGF-β signaling pathway in the ovarian cancer cells, we studied the effects of lithium chloride, an inhibitor of TGF-β pathway, on the cells." (PMID 36393971, 2022). "For example, combining a panel of two AABs (anti-leucine repeat death domain-containing protein (LRDD) and anti-forkhead box A1 (FOXA1) autoantibodies) with serum CA125 levels increased the diagnostic performance by raising the positive rate from 62.7% to 87.1% in ovarian cancer patients." (PMID 36233339, 2022). "However, of the four TFs (PITX1, RARA, FOXF1/A1, and BHLHE41/40) that matched the binding motifs in DEG promoters, only one, FOXA1, has previously been implicated in ovarian cancer specifically." (PMID 34215221, 2021). "In summary, FOXA1 acts as an oncogenic driver in ovarian cancer, promoting proliferation, invasion, and EMT activation." (PMID 41683623, 2026). "This study aimed to elucidate the oncogenic role of FOXA1(forkhead box A1) in ovarian cancer and to evaluate its potential as both a therapeutic target and a diagnostic biomarker." (PMID 41683623, 2026). "Currently, the regulation of the FOXA1 expression is affected by diverse mechanisms such as acetylation and miRNA in ovarian cancer." (PMID 40746724, 2025). "Pats studies have demonstrated that FOXA1, as a transcription factor, affects ovarian cancer prognosis by upregulating gap junction protein β-1 (GJB1)." (PMID 40746724, 2025). "Autoantibodies against leucine repeat death domain-containing protein (LRDD), stanniocalcin-1 (STC1), and forkhead box a1 (FOXA1) were over-expressed in ovarian cancer patients compared to normal controls and showed an AUC of 0.91, 0.88 and 0.82, respectively." (PMID 38275400, 2024). "FOXA1 has oncogenic activity in ovarian cancer, and FOXK2 was recently identified as a promoter of HGSOC stem cell function." (PMID 38704607, 2024). "In the experimental verification, FOXA1 expression levels in four ovarian cancer cell lines were all higher than those in normal ovarian cells." (PMID 36393971, 2022). "Western blot found that the protein level of FOXA1 was significantly upregulated in ovarian cancer cells compared with the normal cell line IOSE80." (PMID 36393971, 2022). "This study is aimed at evaluating serum autoantibodies against four tumor-associated antigens, including LRDD, STC1, FOXA1, and EDNRB, as biomarkers in the immunodiagnosis of ovarian cancer (OC)." (PMID 35273656, 2022). "A proliferation assay, a Transwell assay, an apoptosis assay and animal experiments were used to assess the proliferation, invasion and apoptosis abilities of ovarian cancer cells before and after transfection with FOXA1." (PMID 34991620, 2022). "In our study, we conducted a comprehensive assessment of FOXA1, revealing a potential role of FOXA1 as an indicator of patient prognosis and molecular mechanism of FOXA1 to promote EMT by regulating CTGF/TGF-β pathway in ovarian cancer." (PMID 36393971, 2022). "Over expression of FOXA1 in ovarian cancer is consistent with existing literature, with aberrant expression implicated in tumorigenesis and invasive phenotype." (PMID 33415077, 2020). "Moreover, FOXA1 inhibition enhanced atezolizumab responsiveness and reduced carboplatin resistance in ovarian cancer cells." (PMID 41683623, 2026). "Targeting FOXA1 could enhance immunotherapy efficacy and help overcome chemoresistance in ovarian cancer." (PMID 41683623, 2026). "Unfortunately, there is currently insufficient evidence to confirm the correlation between FOXA1 and ER expressions in ovarian cancer and it is unclear whether the high FOXA1 expression and poor prognosis in ovarian cancer are influenced by ER expression." (PMID 40746724, 2025).
ovarian carcinoma (continued). "It was reported that FOXA1 could be modulated by HDAC3 through the Wnt/β-catenin signaling in ovarian carcinoma." (PMID 37876590, 2023). "In addition, FOXA1 was upregulated in malignant ovarian cancer tissues with substantial differences between the early and advanced stages." (PMID 36393971, 2022). "Past studies have also demonstrated that FOXA1 can interact with the connective tissue growth factor (CTGF) promoter, thereby influencing the development of drug resistance in ovarian cancer." (PMID 40746724, 2025). "FOXA1 and FOXK2 function as oncoproteins in ovarian cancer, while, in contrast, FOXO3a is a tumor suppressor." (PMID 38704607, 2024). "The H-scores for FOXA1 and HDAC3 staining in FIGO stage III-IV were noticeably higher and predicted adverse clinical outcomes in patients with ovarian cancer." (PMID 34991620, 2022). "Among all the ovarian cancer cell lines tested (i.e., OVCAR-3/A2780/3AO/SKOV-3), both transcriptional and translational levels of FOXA1 were highest in OVCAR3, followed by 3AO and SKOV-3, and then A2780." (PMID 36393971, 2022). "To confirm the binding of our identified TFs in ovarian cancer, we performed ChIP-seq experiments for FOXA1, PITX1, and ERα in the ovarian cancer cell line PEO4, derived from a poorly differentiated serous adenocarcinoma." (PMID 34215221, 2021). "The expression levels of HDAC3 and FOXA1 were significantly increased in ovarian cancer recurrence (HDAC3: p < 0.001, FOXA1: p = 0.002) and predicted adverse clinical outcomes in patients with ovarian cancer (HDAC3: p < 0.001, FOXA1: p < 0.001)." (PMID 34991620, 2022). "In this study, we wanted to explore the function of FOXA1 in ovarian cancer and the relationship between HDAC3 and FOXA1.The expression of HDAC3 and FOXA1 was detected by immunohistochemical staining of primary lesions from 127 epithelial ovarian carcinoma patients." (PMID 34991620, 2022).
triple-negative breast carcinoma (16 papers, 2014 to 2026). An invasive breast carcinoma which is negative for expression of estrogen receptor (ER), progesterone receptor (PR), and human epidermal growth factor receptor 2 (HER2). "High JAM-A expression was more associated with the small number of triple-negative breast cancer cases; high FOXA1 and HER3 were highly associated with the Luminal A subtype; and high β-catenin was not significantly correlated with any one molecular subtype." (PMID 33669586, 2021). "Thus, loss of SNAI1 in the context of triple-negative breast carcinoma cells promotes an intermediary luminal progenitor phenotype that gains differentiation plasticity based on the dual transcriptional action of FOXA1 and AR." (PMID 36171192, 2022). "Some studies show that high expression of the SETD3 gene is associated with poor survival in triple-negative breast cancer, while HOXB3 and FOXA1 were identified as indicators of better prognosis." (PMID 34416858, 2021). "In addition, there is evidence indicating the role of the FOXA1 gene in the development of chemoresistance and the existence of a FOXA1-positive chemotherapy refractory triple-negative breast cancer (TNBC) subtype." (PMID 41283251, 2025). "The non-basal-like subtype of triple-negative FMCs that coexpresses AR and FOXA1 (the AR+ FOXA1+ CK14– subgroup) could represent the equivalent of the luminal-AR subgroup of human triple-negative breast cancer." (PMID 31888566, 2019). "We identified an AR+ FOXA1+ CK14– subgroup of triple-negative FMCs that might correspond to the luminal-AR subgroup of human triple-negative breast cancers." (PMID 31888566, 2019). "PCGF5 is also a component of the PRC1 (non-canonical PRC1) complex: overall, PRC1 components can interact with oestrogen receptor alpha (ERα), and the factor FOXA1 in ER-positive breast cancer cells, as well as with BRD4 in triple-negative breast cancer cells." (PMID 40867231, 2025). "AR and FOXA1 expression were evaluated by immunohistochemistry in 333 non-metastatic triple-negative breast cancers (TNBC)." (PMID 29880907, 2018).